MTOR (mechanistic target of rapamycin kinase)
Diseases named in the same sentence as MTOR in open-access papers (continued):
Sharing a sentence is not in itself a finding about the gene and the disease.
cancer (continued). "It is also suggested that a low-carbohydrate diet possibly slows down the growth of cancer cells by reinforcing the inhibitory effects on the mechanistic target of rapamycin (mTOR) pathway." (PMID 31447604, 2019). "Considering the key role of mTOR in cell proliferation and differentiation, its deregulation contributes to cancer onset and progression." (PMID 30987378, 2019). "This highlights the critical role for mTOR signaling in drug resistance and the urgent need to identify and validate alternative functions of mTOR in order to improve the outcome of targeted cancer therapies." (PMID 31285446, 2019). "Since this is a gradual process, pan PI3K blockers, subtype-specific PI3K blockers, PI3K/mTOR double blockers, AKT blockers, and mTOR blockers have been developed to counteract the pathway’s influence on cancer formation." (PMID 31226829, 2019). "In summary, our study demonstrates that PC1 regulates cell proliferation and migration and interacts with mTOR and Jak signalling in various cancer cell lines." (PMID 31251475, 2019). "Recent meta-analyses strongly indicate that the defined and controlled inhibition of mTOR activity reduces the incidence of a variety of cancers." (PMID 30609721, 2019). "Considering that DNA-DSB is the most lethal type of cell death after radiation, the activation of the PI3K/AKT/mTOR pathway can endorse the resistance of cancer cells to RT through enhancing DNA damage repair." (PMID 31430901, 2019). "An aberrant activation of the PI3K/AKT/mTOR pathway is frequently found in many types of cancer and contributes to their malignant growth and therapy resistance." (PMID 31058807, 2019). "An orally-active compound XL765 is well established as PI3K/mTOR dual inhibitor and have shown in vitro and in vivo anticancer activity against a variety of cancer types and is undergoing clinical trials." (PMID 31247018, 2019). "The Cancer Genome Altas (TCGA) data revealed the hyperactivation of phosphoinositol 3 kinase (PI3K)/protein kinase B (AKT)/mammalian target of rapamycin (mTOR) (PI3K/AKT/mTOR) pathway in nearly 60% of patients with OvCa." (PMID 31284467, 2019). "As a result, this has specifically stimulated the development of specific PI3K, Akt, and mTOR inhibitors for targeted cancer therapy." (PMID 31370278, 2019). "The AKT/mTOR and MAPK signaling pathways have been widely implicated in carcinogenesis and are targeted by numerous FDA approved chemotherapeutic agents for cancer remission and improved survival." (PMID 31293977, 2019). "In cancer development, mammalian target of rapamycin (mTOR) kinase is a very important factor, and an mTOR ATP site inhibitor, PP242, can inhibit the downstream pathway of mTOR." (PMID 31861979, 2019). "The combination of anti-VEGFR and anti-mTOR is a promising treatment (e.g., lenvatinib + everolimus), and perhaps in the future more combined targeted therapy regimens will be used in cancer." (PMID 31547602, 2019). "Increased expression of cyclin-dependent kinase 2 (CDK2) was also observed in this type of cancer, suggesting its correlation with the Akt/mTOR signaling." (PMID 31370278, 2019). "This gene codes for a member of the mTOR protein complex, which plays a key role in cell growth and proliferation, and dysregulation of this signaling pathway is a common feature in cancers." (PMID 31149338, 2019). "Especially in solid cancers, preclinical tests have shown that the use of PI3K or mTOR inhibitors results in the restoration of sensitivity of cancer to therapy." (PMID 31159225, 2019). "PI3Ks and their downstream mediators AKT and mTOR constitute the core component of the PI3K/AKT/mTOR signaling pathway which is precisely controlled under normal physiological conditions and is a frequently hyperactivated pathway in cancer." (PMID 30627420, 2019). "mTOR/Akt/p70S6K signaling can halt and regulate cellular catabolic processes such as autophagy, which is frequently dysregulated in cancer and metabolic disorders." (PMID 31752184, 2019).
cancer (continued). "Recent investigations demonstrated that SDF-1 and CCL21 chemokines through their cognate receptors CXCR4 and CCR7, signals to mTOR pathway in other cancers." (PMID 30518812, 2019). "Genetic alterations that deregulate mTOR signalling lead to metabolic reprogramming, resulting in the development of several cancers including those of the head and neck." (PMID 30970654, 2019). "Here, we update recent advances in exploring mTOR signaling and the development of mTOR inhibitors for cancer therapy." (PMID 31277692, 2019). "Recently, we have shown that when using solid lipid curcumin particles (SLCPs), stronger anti-cancer effects and the greater inhibition of the PI3k/Akt/mTOR pathway in human GB cell were observed than when natural Cur was used." (PMID 31841506, 2019). "Numerous clinical trials are ongoing to evaluate the efficacy of mTOR inhibition for cancer treatment." (PMID 31817676, 2019). "Matrine administration obviously decreased the phosphorylation levels of ERK1/2, MEK1/2, PI3K, Akt, mTOR, FAK, RhoA, VEGFR2 and Tie2 in vivo, and then accordingly retarded cancer associated signaling transduction." (PMID 31601793, 2019). "An analysis of publicly available RNA-seq data from a range of human cancers suggests that CDK8 levels are highly correlated with the levels of members of the mTOR pathway." (PMID 31628323, 2019). "PI3K/Akt/mTOR signalling pathway is important to regulate proliferation, differentiation and migration of cancer cells." (PMID 31230505, 2019). "While some of the mTOR inhibitors have been approved to treat human cancer, more mTOR inhibitors are being evaluated in clinical trials." (PMID 31277692, 2019). "The PI3K/AKT/mTOR, Ras/Raf/MAPKs, and NF-κB signaling pathways have been shown to drive oncogenesis in cancer." (PMID 31783709, 2019). "AMPK activation in cancer cells is known to modulate downstream mTOR pathway leading to tumor growth inhibition." (PMID 31618928, 2019). "Supplementing etoposide with the inhibitor of its emulator mTOR with rapamycin has already been shown to reduce the survival of cancer cells in a mouse model of AML." (PMID 31523390, 2019). "The Akt/mammalian target of rapamycin (Akt/mTOR) pathway is the most frequently mutated pathway in human cancers, including GBM, and is correlated with tumorigenesis, drug resistance, cancer progression, and transformation." (PMID 30769863, 2019). "A recent report reveals that the mammalian target of rapamycin (mTOR) inhibition protects cancer cells from apoptosis during nutrient limitation." (PMID 30935141, 2019). "The PI3K/AKT/mTOR signaling pathway is a critical intracellular signaling cascade involved in a number of hallmarks of cancer, such as cell proliferation, survival, growth, motility, and metabolism." (PMID 31223424, 2019). "Consistent with its physiological role, the PI3K/AKT/mTOR pathway has been found to be hyperactivated in many types of cancer." (PMID 31547471, 2019). "The AKT/mTOR signaling pathway is one of the survival regulatory pathways in both normal and cancer cells, and it can negatively regulate autophagy." (PMID 31540489, 2019). "As a vital signaling molecule that controls cell proliferation and growth under physiological conditions, mTOR is constitutively active in multiple types of cancer." (PMID 30927928, 2019). "Inhibiting mTOR, we inhibit not only the survival, proliferation, senescence, and metabolism of the cancer cell but also the ability to activate the osteoclast." (PMID 31766386, 2019). "mTOR inhibitors (mTORi) were initially designed as anti-cancer drugs, as well as immunosuppressive agent, because of their ability to suppress the growth and proliferation of tumor cells in mice." (PMID 30972289, 2019).
cancer (continued). "PI3K/AKT/mTOR regulates cell proliferation, differentiation, cellular metabolism and cancer cell survival." (PMID 31632198, 2019). "IQGAP1 acts as a scaffold to modulate important signal transduction in PI3K/mTOR/AKT and MAPK pathways and is highly associated with cancers, including HNSCC36–38." (PMID 31798960, 2019). "There is accumulating evidence that the PI3K/AKT/mTOR pathway is frequently activated in diverse cancer and drugs that target the PI3K/Akt/mTOR signaling pathway have the potential to induce apoptosis in cancer cells." (PMID 30429232, 2019). "Several drugs are already being used in clinics or in clinical trials to induce autophagy for the treatment of malignant tumors, such as mTOR inhibitor, vitamin D3 analog, and imatinib." (PMID 31319622, 2019). "As a result, guava leaf not only induced significant apoptotic effects, but also suppressed constitutive activation of PI3K/AKT/mTOR/S6K1 in PC3 cancer cells." (PMID 31597327, 2019). "The mTOR pathway is essential for the regulation of synthesis of proteins that are critical for the growth and survival of cancer cells and therefore supports rapid progression of the cell-cycle in TNBCs." (PMID 30626087, 2019). "The reduction of GLI1 protein in the nucleus after dual PI3Kα and mTOR inhibition indicates a requirement for PI3Kα and mTOR activities to sustain nuclear GLI1 in HH-driven cancers." (PMID 31492956, 2019). "Among these molecules, we emphasize the increased expression of CD44 which was previously assigned as cancer stem cell marker and of mTOR, a characteristic indicator of the engagement of the PD-1:PD-L1 pathway." (PMID 31681332, 2019). "This classic route consists of two signaling pathways, PI3K/AKT and mTOR, which are important in regulating the cell cycle and directly related to cellular proliferation, tumors, and cancer." (PMID 31533276, 2019). "Although apoptosis has been referred to as the main route for HDACIs-induced cancer cell death, autophagy stimulation has also been implicated, being the inactivation of PI3K/Akt/mTOR signaling the most described pathway." (PMID 31635099, 2019). "Most cancer cells are resistant to the 1st generation mTOR inhibitors (Rapalogs) which particularly target mTORC1 which makes the insensitivity of mTORC2 a possible opening for drug discovery." (PMID 31075885, 2019). "PI3K/AKT/mTOR signaling is an important intracellular pathway that is frequently activated in diverse cancers." (PMID 31632198, 2019). "The targeting of mTOR signalling as a front-line therapy or as an alternative treatment to overcome resistance is of interest in many cancer types." (PMID 35582282, 2019). "Studies have shown that the inhibition of components such as RICTOR, RAPTOR, or mTOR significantly reduces the proliferation of cancer cells and offsets progression in the cell cycle." (PMID 31075885, 2019). "In summary, the majority of NPs resulted in mTOR inhibition in various types of both cancer and normal cells." (PMID 30642006, 2019). "Previous studies showed that PD-L1 was regulated by the phosphoinositide-3-kinase–protein kinase B (PI3K)/protein kinase B (AKT)/mammalian targets of rapamycin (mTOR) pathway, which promoted cancer protein synthesis, survival, proliferation, and apoptosis." (PMID 31878272, 2019). "An example is involvement of phosphoinositide 3 kinase/Akt/ mammalian target of rapamycin (PI3K/Akt/mTOR) signaling pathway, an essential axis in cell proliferation, metabolism, growth and autophagy in pathogenesis of AD and cancer." (PMID 30881282, 2019). "Their activation also tightly depended on the mammalian target of rapamycin (mTOR) activation, which indicated that mTOR can be critical in regulating cancer metabolism on the downstream of RAC1." (PMID 31314174, 2019).
cancer (continued). "Use of phytochemicals alone or in combination for treatment can help to regulate aberrant molecular pathways in cancer cells, such as the NF-κβ and the Akt/mTOR pathway." (PMID 30959836, 2019). "The previous studies showed that mTOR was considered as a biomarker of cancer, immune disease, degenerative diseases, and metabolic diseases." (PMID 31485275, 2019). "From a combinatory point of view rapamycin and metformin are able to synergize their activities against cancer cells, since this last one inhibits miR-21-5p which induces signaling of mTOR, a rapamycin-target." (PMID 31921661, 2019). "For example, mTOR activation in cancer cells upregulates the expression of PKM2 through HIF-1α mediated transcriptional activation of PKM, and Myc-hnRNPs-mediated splicing of PKM pre-mRNA, in favor of PKM2." (PMID 30857125, 2019). "The most known function of PTEN is as the negative regulator of the PI3K/Akt/mTOR pathway, which is a crucial signal transduction pathway for cancer cell growth." (PMID 31591355, 2019). "We also explored the potential role of miR-21-3p in other cancer types with high levels of mTOR activity." (PMID 31410193, 2019). "In complex with rapamycin, FKBP12 interacts with mammalian target of rapamycin (mTOR) and inhibits its roles in regulating cell growth and cancer progression." (PMID 31428819, 2019). "Several reports have documented that co-targeting growth factor receptors and mTOR exerts cooperative anti-cancer effects in various cancer types, including TNBC." (PMID 31388935, 2019). "Though the specific mechanism still remains to be discovered, it is reasonable to predict that drugs targeting the overly activated mTOR pathway, especially mTORC2, would have a clinical significance in cancer treatment." (PMID 34691993, 2019). "In turn, p53LOH upregulates the mTOR pathway to further enhance cancer cells fitness and enable their survival after DNA damage." (PMID 31799437, 2019). "Autophagy is constitutively activated in cancer cells through the deregulation of PI3K/Akt/mTOR molecular axis and AMP-activated protein kinase (AMPK) signal transduction, which contributes to the metabolic reprogramming of cancer cells." (PMID 31370155, 2019). "Recent studies have shown that mTOR plays a critical role in the regulation of tumor cell motility, invasion, and cancer metastasis." (PMID 31594284, 2019). "Several studies have reported that activation of AMPK induces autophagic cell death in various cancer cells via suppression of mTOR." (PMID 31611925, 2019). "mTOR also serves as a downstream effector for many frequently mutated prooncogenic pathways, such as Ras/Raf/MAPK pathway, resulting in the hyperactivation of mTOR pathway in numerous human cancers." (PMID 30857853, 2019). "Deregulation of the PI3K/Akt/mTOR pathway contributes to activation of cell proliferation, adhesion, migration, invasion, metabolism, and survival in many cancers." (PMID 31698699, 2019). "The activity of the PI3K/AKT/mTOR axis contributes to tumorigenesis, tumor progression, and resistance to therapy in most human cancer types." (PMID 31262325, 2019). "The following subsections focus on the use of mTOR inhibitors in human clinical trials in different cancer types." (PMID 31569540, 2019). "The serine/threonine kinase AKT transfers survival signals through phosphorylated mTOR, p70S6K, and 4EBP1 to inhibit the apoptosis of cancer cells, and p70S6K can also accelerate cell cycle progression in cancer cells." (PMID 31139014, 2019). "XL765 (Exelixis, Inc., South San Francisco, CA USA) is an orally-active, potent and selective class-I PI3K/mTOR inhibitor which has demonstrated broad anti-cancer efficacy." (PMID 31247018, 2019). "Our results are consistent with the previous reports of chemotherapeutic agents providing survival benefits in cancers by modulating AKT/mTOR and MAPK signaling pathways." (PMID 31293977, 2019).
cancer (continued). "The PI3K/Akt/mechanistic target of rapamycin kinase (mTOR) signaling pathway promotes cancer cell proliferation and survival, especially through its essential role in cell-cycle progression." (PMID 31717324, 2019). "In response to metabolic stress in cancer cells, the balance between cell growth and autophagy is regulated primarily by the mammalian target of rapamycin (mTOR)." (PMID 30754624, 2019). "This high-risk group of tumor cases was marked by upregulation of known cancer-related pathways (e.g. mTOR signalling)." (PMID 31747912, 2019). "Putative harmful mutations were observed in genes involved in well-known cancer-related pathways, including PI3K-Akt/mTOR signalling, Proteoglycans in cancer, FoxO signalling, Jak-STAT signalling, Chemokine signalling and Focal adhesion." (PMID 31429737, 2019). "Recently, it was demonstrated that the generation of α-KG, resulting from the catabolism of glutamine, was critical for the activation of mTOR in cancer cell lines of cervical carcinoma and osteosarcoma." (PMID 30634602, 2019). "Serine/threonine kinase Akt (protein kinase B) plays an important role in the PI3K/Akt/mTOR pathway, and abnormally activated Akt is commonly seen in cancer, including metastatic castration-resistant prostate cancer (mCRPC)." (PMID 31227862, 2019). "In this regard, the elevation of the hypoxia-responsive Ddit4 in Spalax, compared to its down-regulation in mice, should also be noted, as up-regulation of Ddit4 expression mediates mTOR inhibition and growth inhibition in cancer cells." (PMID 30621584, 2019). "Other groups have in fact reported that, in cancer cells as well as in cancer specimens, mTOR inhibition with rapamycin induces feedback activation of the AKT survival pathways." (PMID 31464606, 2019). "The combination of PI3K-Akt-mTOR inhibition and metabolic targeting is now under investigation for other cancers, and our results suggest that this combined strategy should be further considered in AML, but possibly only for selected subsets of patients." (PMID 31240133, 2019). "Various studies have already shown that deregulation of the mTOR pathway is present in many cancers." (PMID 31817676, 2019). "Maf 1 activates the PTEN transcription leading to reduce Akt-mTOR pathway and suppressing the cancer proliferation." (PMID 31556759, 2019). "Most notably, similar trends in the Akt/mTOR pathways and optical redox ratios were observed in cancer." (PMID 31149027, 2019). "Matrine treatment retarded the cancer associated signaling transduction by decreasing the phosphorylation levels of ERK1/2, MEK1/2, PI3K, Akt, mTOR, FAK, RhoA, VEGFR2, and Tie2 in vitro and in vivo." (PMID 31601793, 2019). "Molecular approaches have been used to establish the role of the components of the mTOR pathway in cancer development." (PMID 31075885, 2019). "Fatty acid metabolism is also being targeted in combination with mTOR inhibitors for cancer therapy." (PMID 31817676, 2019). "The PI3K/Akt/mTOR pathway regulates a variety of cellular functions in cancer, such as cell growth, survival, proliferation." (PMID 31467400, 2019). "In view of the central role of PI3K/Akt/mTOR in cancer cell proliferation in many tumour types there is much interest in oncology in the use of inhibitors targeting components of this pathway." (PMID 30056610, 2019). "Another miRNA, miR-99a, which was downregulated in the diseased sheep, appears to target AKT1 (which has an important role in the PI3K-Akt pathway) and inhibits cancer cell proliferation by targeting mTOR." (PMID 30658565, 2019). "The PI3K/AKT/mTOR pathway is one of the most frequently dysregulated pathways in tumor progression, which makes this pathway an attractive target for cancer therapy." (PMID 31223424, 2019). "Some molecules like mTOR play a crucial role both in the metabolism of cancer cells and activated Th cells, which has been investigated earlier." (PMID 30766532, 2019).